MTMR1 (myotubularin related protein 1)
Description:
Lipid phosphatase that specifically dephosphorylates the D-3 position of phosphatidylinositol 3-phosphate, generating phosphatidylinositol. Could also dephosphorylate phosphatidylinositol 3,5-bisphosphate to produce phosphatidylinositol 5-phosphate.
Tractability: Antibody: UniProt places it where antibodies can reach, with medium confidence; its Gene Ontology location is reachable by antibodies, with medium confidence. PROTAC: ubiquitination databases record sites on it; its protein half-life has been measured.
Target class: Enzyme; Hydrolase
Gene: Protein-coding gene on chromosome X (150,692,971 to 150,765,165, forward strand). Ensembl gene ENSG00000063601.
Subcellular location: Cell membrane; Cytoplasm
Subcellular location (Human Protein Atlas): Vesicles
Pathways (Reactome):
Metabolism: Synthesis of PIPs at the plasma membrane
Signal Transduction: RHOF GTPase cycle
Gene Ontology:
Molecular function: phosphatidylinositol-3,5-bisphosphate 3-phosphatase activity; phosphatidylinositol-3-phosphate phosphatase activity; protein binding; protein homodimerization activity; phosphatidylinositol phosphate phosphatase activity
Biological process: phosphatidylinositol dephosphorylation; protein destabilization; regulation of phosphatidylinositol dephosphorylation; phosphatidylinositol biosynthetic process
Cellular component: cytoplasm; cytosol; membrane; plasma membrane
Homologues: Orthologues: chimpanzee MTMR1 (99% identical), macaque MTMR1 (99% identical), rabbit MTMR1 (94% identical), pig MTMR1 (94% identical), mouse Mtmr1 (92% identical), dog MTMR1 (90% identical), rat Mtmr1 (89% identical), tropical clawed frog mtmr1 (85% identical), zebrafish mtmr1a (69% identical), zebrafish mtmr1b (66% identical), Drosophila melanogaster mtm (48% identical), Caenorhabditis elegans mtm-1 (37% identical), and 10 more. Paralogues in human: MTMR2 (66% identical), MTM1 (52% identical), MTMR3 (31% identical), MTMR8 (31% identical), MTMR6 (30% identical), MTMR7 (30% identical), MTMR4 (30% identical), SBF1 (28% identical), SBF2 (28% identical), MTMR9 (26% identical), MTMR10 (23% identical), MTMR12 (21% identical), and 1 more.
Diseases named in the same sentence as MTMR1 in open-access papers:
MTMR1 is named in the same sentence as 9 diseases in open-access papers, as found by Europe PMC text mining. Sharing a sentence is not in itself a finding about the gene and the disease. The quoted sentences say what the papers report.
myotubular myopathy (5 papers, 2009 to 2024). "Similarly a conserved miR-181b MRE was also identified in MTMR1, previously identified as an important regulator of myogenesis through its association with muscular disorders such as myotubular myopathy and congenital myotonic dystrophy, though its exact biological role is still unclear." (PMID 23083446, 2012). "Another significant BIN1_SH3 binder detected by our assay is MTMR1, a close paralog of myotubularin (MTM1) whose mutation can cause the X-linked form of CNM also called myotubular myopathy." (PMID 38995680, 2024). "This implies that increasing the expression of either MTMR1 or MTMR2 in patient muscle is a viable potential treatment strategy for myotubular myopathy." (PMID 19197364, 2009).
myotonic dystrophy (2 papers, 2016 to 2018). An inherited progressive disorder affecting the muscles. "These biochemical data for MTMR1 could reveal the cellular mechanism underlying myotonic dystrophy." (PMID 27018598, 2016). "MTMR1 gene is a phosphatase which represents a novel target for abnormal mRNA splicing in myotonic dystrophy, and its abnormal expression is proved to be related to impair muscle differentiation." (PMID 29392408, 2018).
Charcot-Marie-Tooth neuropathy (1 paper, 2009). "Mutations in MTMR family proteins are associated with the human neuromuscular disorders X-linked myotubular myopathy (myotubularin and MTMR1) and type 4B Charcot-Marie-Tooth neuropathy (MTMR2 and MTMR13)." (PMID 19325702, 2009).
tumor (1 paper, 2025). "Of these, five were present in at least one tumor from each cohort: IGLL5 p.L28M, MTMR1 p.R389Q, MYD88 p.S206C, PABPC3 p.K231E." (PMID 40634688, 2025).
MTMR1 also shares sentences with these, for which no sentence is quoted: Hunter syndrome (1 paper); muscular disorders (1); myopathy (1); Obesity (1); X-linked myotubular myopathy (1).